DMXL2 (Dmx like 2)
Description:
May serve as a scaffold protein for MADD and RAB3GA on synaptic vesicles. Plays a role in the brain as a key controller of neuronal and endocrine homeostatic processes (By similarity).
Synonyms: KIAA0856; RC3; DFNA71; DEE81; EIEE81; PEPNS
Tractability: Antibody: UniProt places it where antibodies can reach, with high confidence. PROTAC: ubiquitination databases record sites on it; its protein half-life has been measured.
Gene: Protein-coding gene on chromosome 15 (51,447,711 to 51,622,981, reverse strand). Ensembl gene ENSG00000104093.
Subcellular location: Cytoplasmic vesicle, secretory vesicle, synaptic vesicle membrane; Cytoplasmic vesicle, secretory vesicle, neuronal dense core vesicle
Subcellular location (Human Protein Atlas): Vesicles; Cytosol
Gene Ontology:
Molecular function: small GTPase binding
Biological process: vacuolar acidification
Cellular component: extracellular region; synaptic vesicle; RAVE complex; neuronal dense core vesicle; synaptic vesicle membrane
Genetic constraint (gnomAD): Loss-of-function variants: 80 observed, 267.65 expected, observed/expected ratio (o/e) 0.3, 90% interval 0.25 to 0.36. The upper end of that interval is the gene's LOEUF score, 0.36, which puts it in group 1 of 6, group 1 being the genes least tolerant of losing a copy. Missense variants: 2,837 observed, 3,364 expected, observed/expected ratio (o/e) 0.84, 90% interval 0.82 to 0.87. Synonymous variants: 1,157 observed, 1,176.5 expected, observed/expected ratio (o/e) 0.98, 90% interval 0.94 to 1.03.
Gene-disease validity (ClinGen):
ClinGen rates the evidence that DMXL2 causes each of these diseases.
nonsyndromic genetic hearing loss (autosomal dominant): Limited.
Homologues: Orthologues: chimpanzee DMXL2 (99% identical), macaque DMXL2 (99% identical), dog DMXL2 (95% identical), pig DMXL2 (94% identical), rat Dmxl2 (93% identical), mouse Dmxl2 (93% identical), rabbit DMXL2 (89% identical), guinea pig DMXL2 (89% identical), tropical clawed frog dmxl2 (76% identical), zebrafish dmxl2 (71% identical), Drosophila melanogaster Rbcn-3A (41% identical), Caenorhabditis elegans rbc-1 (31% identical). Paralogues in human: DMXL1 (55% identical).
Diseases named in the same sentence as DMXL2 in open-access papers:
DMXL2 is named in the same sentence as 37 diseases in open-access papers, as found by Europe PMC text mining. Sharing a sentence is not in itself a finding about the gene and the disease. The quoted sentences say what the papers report.
breast carcinoma (9 papers, 2015 to 2026). "As being ubiquitously expressed, DMXL2 is associated with several conditions and is regarded as a functional biomarker of estrogen receptor alpha (Erα) positive breast cancer." (PMID 38162630, 2023). "DMXL2 gene dysfunction underlies various human diseases, including breast cancer, non-syndromic hearing loss, and polyendocrine-polyneuropathy syndrome, demonstrating the large range of potential actions of DMXL2." (PMID 30735494, 2019). "DMXL2 is a transmembrane protein that is overexpressed in resistant breast cancer cell lines, is an activator of the epithelial-to-mesenchymal transition, and is a potential new biomarker for hormone-positive breast cancer." (PMID 40535770, 2025). "DMXL2 has also been proposed as a potential therapeutic target for breast cancer and oral mucosal melanoma." (PMID 38283355, 2023). "It has been reported that reduction in the expression of DMXL2 will decrease the notch signaling significantly, thus, improving the outcome of breast cancer treatment." (PMID 36268271, 2022). "Studies have shown that DMXL2 is highly expressed in resistant breast cancer, and DMXL2 enhances the transition of the epithelium into mesenchymal via the activation of notch signaling." (PMID 36268271, 2022). "The significant SNPs, rs114516513 in DMXL2 was observed in the study, and previous expression studies indicate the need of further studies in the Arab ancestries with breast cancer." (PMID 36268271, 2022). "Significantly, downregulation of either DMXL2 or V-ATPase activity reduces upregulation of Notch targets and invasion phenotypes in breast cancer cell lines." (PMID 34249946, 2021). "Overexpression of DMXL2 has been observed in breast cancer patients that are resistant to endocrine therapy." (PMID 34249946, 2021). "In another paper, it was declared that DMXL2 was increased in some endocrine therapy resistant breast cancer cells where DMXL2 promoted EMT via activating Notch signaling through V-type ATPase dependent acidification." (PMID 32636747, 2020). "Our results demonstrate that DMXL2 regulates Notch cleavage and chromatin recruitment, epithelial to mesenchymal transition, invasion and migration of endocrine therapy resistant breast cancer cells." (PMID 26093085, 2015). "Based on these findings and on the highlight of our recent work, we wanted to explore the role of DMXL2 in driving the mesenchymal switch in therapy resistant breast cancer." (PMID 26093085, 2015). "This warrants further investigation focusing on the development of monoclonal antibodies targeting DMXL2 as an alternative option to block Notch in breast cancer." (PMID 26093085, 2015). "We show for the first time that DMXL2 protein levels are significantly increased in ERα positive breast cancer patients that progress after endocrine therapy." (PMID 26093085, 2015). "For each patient we measured DMXL2 in untreated primary breast cancer samples and matched metastatic samples resistant to endocrine therapy using IHC which revealed that DMXL2 had a membrane-cytoplasmic staining." (PMID 26093085, 2015). "Here, we demonstrate that DMXL2 is overexpressed in a subset of endocrine therapy resistant breast cancer cell lines where it promotes epithelial to mesenchymal transition through hyper-activation of Notch signalling via V-ATPase dependent acidification." (PMID 26093085, 2015). "Notably, DMXL2 increases dramatically during breast cancer progression, in agreement with our cell line model." (PMID 26093085, 2015). "Previous evidence suggests that DMXL2 might regulate Notch in breast cancer cells and that this regulation is dependent on the interaction between DMXL2 and the V-ATPase pump." (PMID 26093085, 2015). "Hence, DMXL2 can be identified as novel biomarker in ERα positive breast cancer patients." (PMID 26093085, 2015). "DMXL2 drives NOTCH signalling and the mesenchymal switch in endocrine therapy-resistant breast cancer cells when overexpressed." (PMID 38162630, 2023).
breast carcinoma (continued). "Here we demonstrate that DMXL2 overexpression drives Notch signalling and EMT transition in endocrine therapy resistant breast cancer cells." (PMID 26093085, 2015). "DMXL2 is a novel regulator of Notch signalling not yet investigated in breast cancer." (PMID 26093085, 2015).
hearing loss (6 papers, 2018 to 2023). "Biallelic loss-of-function DMXL2 variants are also known to cause Ohtahara syndrome characterized by neurologic deficits including intellectual disability, developmental delay, hearing loss, polyneuropathy and also facial dysmorphisms." (PMID 33924653, 2021). "Some researchers point out that the Arg2417His variant in DMXL2 is associated with dominant nonsyndromic hearing loss." (PMID 31692290, 2019). "A recent study identified a heterozygous missense variant of DMXL2 that is associated with dominant, non-syndromic hearing loss in humans." (PMID 30258843, 2018). "DMXL2: DMXL2 (MIM 612186; 15q21.2) was recently identified to have missense variants causing AD nonsyndromic hearing loss in Chinese and Cameroonian families." (PMID 33924653, 2021). "Family studies have led to the identification of many variants involved in adult-onset Mendelian hearing loss (for example, MIR96, DMXL2, reviewed in), but these tend to be very rare or even private variants, and are unlikely to explain all of the hearing loss seen in humans." (PMID 37163093, 2023). "Currently there is no other established model to study DMXL2-related human hearing loss." (PMID 30258843, 2018).
Ohtahara syndrome (6 papers, 2021 to 2025). "Mutations in subunits of the mRAVE complex cause similar neurodevelopmental phenotypes, exemplified by DMXL2 mutations in Ohtahara syndrome and ROGDI mutations in Kohlschutter-Tonz Syndrome." (PMID 41509426, 2025). "Mutations in their encoding genes can lead to neurodegenerative disorders, such as Parkinson’s disease (ATP6AP2) and Ohtahara syndrome (DMXL2)." (PMID 39273013, 2024). "Loss of DMXL2 is associated with impaired v-ATPase activity in multiple experimental models, while biallelic mutations have been found in patients from three unrelated families with severe and rapidly progressing DEE associated with Ohtahara syndrome and premature death." (PMID 39273013, 2024).
developmental delays (3 papers, 2019 to 2025). "Although the precise role of Rabconnectin-3 in modulating exocytosis has remained enigmatic, the observation that DMXL2 haplo-insufficiency or WDR7 gene deletion cause developmental delays and mental retardation suggests a critical neurophysiological function of Rabconnectin-3." (PMID 31253182, 2019). "However because patient ID5 only has a heterozygous DMXL2 variant, the developmental delay may also be due to other causes, such as variants in CCDC186 (MIM 619249; 10q25.3), ZRF2 or MCM3AP (MIM 603294; 21q22.3)." (PMID 33924653, 2021).
gonadotropic deficiency (3 papers, 2014 to 2020). "This is a new mechanism of gonadotropic deficiency in mice, which is likely similar in DMXL2 mutated patients." (PMID 28209974, 2017). "An investigation of gonadotropic axis function in adult nes-Cre;Dmxl2–/wt mice showed that the partial gonadotropic deficiency was associated with the presence of a smaller total number of GnRH-ir neurons." (PMID 25248098, 2014).
Infertility (3 papers, 2014 to 2022). "Investigations in a DMXL2-deficient mouse line showed that haploid deficiency of DMXL2 in neurons causes infertility due to a partial GnRH deficiency." (PMID 35456411, 2022). "The delayed puberty and infertility observed in nes-Cre;Dmxl2–/wt mice was therefore due largely to a hypothalamic defect." (PMID 25248098, 2014).
Intellectual disability (3 papers, 2017 to 2025). "A recent study reported an important role of Dmx-like 2 (DMXL2), a gene encoding rabconnectin-3α vesicular protein, in human subjects with mental retardation and neuroendocrine impairment of reproduction." (PMID 27957681, 2017). "Variants of the genes encoding the members of the Rabconnectin-3 complex, i.e., V-ATPases, DMXL2, and WDR7, result in epilepsy, intellectual disability, autism spectrum disorder, or enamel defects." (PMID 41153423, 2025).
polyendocrine-polyneuropathy syndrome (3 papers, 2017 to 2024). "Pathogenic mutations in the DMXL2 gene cause the autosomal dominant deafness type 71 (OMIM # 617605), and the autosomal recessive developmental and epileptic encephalopathy type 81 (OMIM # 618663) and polyendocrine-polyneuropathy syndrome (OMIM # 616113)." (PMID 37012327, 2024).
polyneuropathy (3 papers, 2018 to 2021). A disease or disorder affecting more than one nerve. "A role for this protein in reproductive function has also been suggested in humans, in which DMXL2 has been implicated in a complex syndrome of congenital hypogonadotropic hypogonadism (CHH) associated with polyneuropathy and glucose metabolism disorders." (PMID 30735494, 2019). "DMX like 2 (DMXL2) mutations are associated with congenital HH, other endocrine deficiencies and polyneuropathies." (PMID 29730183, 2018).
autism spectrum disorder (2 papers, 2019 to 2025). A spectrum of developmental disorders that includes autism, and Asperger syndrome. "Disruption of DMXL2 may predispose to NDDs including autism spectrum disorder." (PMID 30732576, 2019).
Hypoglycemia (2 papers, 2019 to 2023). A decreased concentration of glucose in the blood. "Knockout experiments in mice showed that loss of DMXL2 function triggered severe hypoglycemia and death in neonates." (PMID 37649052, 2023). "As hypoglycemia affected the male pups only and neonatal lethality displayed no sex bias, it appears unlikely that this feature is responsible for the lethality of Dmxl2 knockout." (PMID 30735494, 2019). "Intriguingly, hypoglycemia was observed only in male KO pups, highlighting the sex-specific nature of DMXL2 function in glucose homeostasis and, possibly, in adrenal sex-specific functions." (PMID 30735494, 2019). "A glucose metabolism disorder was also detected, with male Dmxl2 KO pups displaying severe hypoglycemia." (PMID 30735494, 2019). "Interestingly, neonatal Dmxl2 KO pups present signs of metabolic/homeostasis problems, such as hypoglycemia in particular." (PMID 30735494, 2019).
major depressive disorder (2 papers, 2019). An episode of depression lasting two or more weeks without an intervening episode of mania. "There is also evidence of enrichment for rare sequence variants in DMXL2 in major depressive disorder." (PMID 30732576, 2019). "DMXL2, Dmx Like 2, is involved in synaptic vesicle exocytosis in major depressive disorder patients." (PMID 31118907, 2019). "DMXL2 has also been found to be related to co-occurring cardiovascular disease under selective serotonin reuptake inhibitors (SSRI) treatments in patients with major depressive disorder." (PMID 31118907, 2019).
Ataxia (1 paper, 2014). Ataxia refers to impaired coordination of voluntary muscle movement. "As patients with the c.5824_5838del of DMXL2 displayed ataxia and mental disability, we investigated whether Dmxl2lox/wt or nes-Cre;Dmxl2–/wt mice displayed neurological defects." (PMID 25248098, 2014).
Gonadotropin deficiency (1 paper, 2014). A reduced ability to secrete gonadotropins, which are protein hormones secreted by gonadotrope cells of the anterior pituitary gland, including the hormones follitropin (FSH) and luteinizing hormone (LH). "We investigated whether the gonadotropin deficiency observed in nes-Cre;Dmxl2–/wt mice was due to GnRH deficiency, by quantifying GnRH mRNA levels in the hypothalamus of nes-Cre;Dmxl2–/wt mice and comparing them with those of WT mice." (PMID 25248098, 2014).
melanoma (1 paper, 2019). A malignant, usually aggressive tumor composed of atypical, neoplastic melanocytes. "Notably, the canine oral melanomas in our series also lacked SF3B1 and GNAQ mutations, and no mutations in POLE, PTPRD, or DMXL2 were found, suggesting that these canine cancers may not represent a faithful genetic model for the subset of human mucosal melanomas with mutations in these genes." (PMID 30664638, 2019).
nonsyndromic sensorineural hearing loss (1 paper, 2024). "This study showed that hair cell knock-out of murine Dmxl2, whose human homolog is responsible for nonsyndromic sensorineural hearing loss DFNA71, resulted in auditory synaptopathy by impairing synaptic endocytosis and recycling." (PMID 39147590, 2024). "Previous human genetic studies identified mutations in DMXL2 as the pathogenic causes for dominant nonsyndromic hearing loss DFNA71 and recessive syndromic hearing loss associated with polyendocrine-polyneuropathy syndrome and developmental and epileptic encephalopathy named Ohtahara syndrome." (PMID 39147590, 2024).
periodontitis (1 paper, 2024). An acute or chronic inflammatory process that affects the tissues that surround and support the teeth. "Given the possible association between DMXL2 and severe periodontitis genes, large-sample verification is needed." (PMID 37435641, 2024). "The allele frequencies at the mutation loci of LFNG, LENG8, NPHS1, HFE, ILDR1, and DMXL2 genes were analyzed in the 15 patients with severe periodontitis." (PMID 37435641, 2024). "We found that the allele loci of NPHS1(rs114615449), ILDR1(rs142746163), and DMXL2(rs3078066) showed significant differences between the severe periodontitis patients and dbSNP 155 (East Asian race) (P < 0.05)." (PMID 37435641, 2024). "Our results indicate that DMXL2 may be a susceptibility gene for the development of severe periodontitis, but further large-sample studies are needed to confirm the results." (PMID 37435641, 2024). "Consequently, we suggest the DMXL2 gene as a possible new candidate susceptibility gene for severe periodontitis." (PMID 37435641, 2024). "According to our gene function prediction analysis based on ARCHS4, DMXL2 may cause the human “periodontitis” phenotype." (PMID 37435641, 2024). "Therefore, we speculate that the DMXL2 gene mutation at the exon level alters the host immune defense response in some patients with severe periodontitis, ultimately causing severe periodontitis." (PMID 37435641, 2024). "Following these analyses, the DMXL2 gene was identified as being associated with stage III and IV periodontitis." (PMID 37435641, 2024). "Our study shows a possible effect of a DMXL2 gene mutation on the risk of stage III and IV periodontitis among Han Chinese individuals, which now needs confirmation in other ethnic groups to determine its generalizability and further experimentation to clarify all involved mechanisms." (PMID 37435641, 2024). "In the present study, we first identified heterozygous mutation loci in the DMXL2 gene in 2 of 15 cases with stage III and IV periodontitis by WES, which shows a possible effect of this gene mutation on the risk of severe periodontitis among Han Chinese individuals." (PMID 37435641, 2024). "Based on the number of cases with shared mutations and correlation analysis results, we found that the DMXL2 gene might be associated with stage III and IV periodontitis." (PMID 37435641, 2024).
schizophrenia (1 paper, 2019). A major psychotic disorder characterized by abnormalities in the perception or expression of reality. "DMXL2 protein dosage insufficiency may therefore result in structural (e.g., abnormal dendritic spines morphology) and/or functional (e.g., impaired transmission) synaptic consequences in humans, as have been observed in other genetic forms of ID, ASD, and schizophrenia." (PMID 30732576, 2019).
infection (1 paper, 2021). The state of being infected such as from the introduction of a foreign agent such as serum, vaccine, antigenic substance or organism. "DOCK11, DIDO1 and DMXL2 were only found in leukocytes during infection with the EuA lineage: these are associated with innate immunity and inflammation activation." (PMID 34141493, 2021).
metabolic disorder (1 paper, 2014). "As DMXL2 loss was also associated with metabolic disorder in the three brothers, the authors examined whether Dmxl2 might affect metabolic balance in mice." (PMID 25247306, 2014).
DMXL2 also shares sentences with these, for which no sentence is quoted: autism (2 papers); deafness (2); neurodevelopmental disorder (2); tumor (2); Anosmia (1); breast tumors (1); cancer (1); cardiovascular disease (1); endolymphatic hydrops (1); epilepsy (1); frontotemporal dementia (1); glucose metabolism disorders (1); hereditary spastic paraplegia (1); juvenile amyotrophic lateral sclerosis (1); Kohlschutter-Tonz Syndrome (1); mucosal (1); mucosal melanoma (1).